IL6 (interleukin 6)
Diseases named in the same sentence as IL6 in open-access papers (continued):
Sharing a sentence is not in itself a finding about the gene and the disease.
leukemia (continued). "The modified LNP can stably transform T cells into IL‐6 knockout CAR‐T cells, kill the tumor cells that highly express CD19, and further reduce the release of IL‐6 and CRS in leukemia in vivo." (PMID 38456710, 2024). "In human differentiated THP-1 cells (a human leukemia monocytic cell line), knockdown of PGAM5 stimulated TNFα and IL-6 secretion in naïve macropahges and increased TNFα, IL-6 and IL-1β in macropahges treated with IL-4 and IL-13 (M2 macrophage)." (PMID 37605246, 2023). "Based on this, the cell viability and immune factors of mouse mononuclear macrophage leukemia cells (RAW264.7) were used for evaluating the immune activity on CMPP, such as nitric oxide (NO), tumor necrosis factor α (TNF-α) and interleukin 6 (IL-6)." (PMID 35681381, 2022). "In this context, it has been reported that thymoquinone consumption moderated the levels of IL-6 and subsequently suppressed MMP-1, MMP-3, VEGF, and decreased TIMP-1 in Leukemia." (PMID 36518397, 2022). "Abnormal cytokine signaling pathways are characteristic of all types of leukemia, especially IL-1, TNF-α, and IL-6, which are considered key cytokines that disrupt hematopoietic cell function and promote the development of inflammation." (PMID 35441668, 2022). "Res and ω-3 PUFA reduced IL-1β, IL-6, TNF-α, CXCL10/IP-10, CCL13/MCP-4 and CCL20/MIP-3α in LPS/IFN-γ activated human leukaemia THP-1 cells, which is indicative of a dampening effect on M1 macrophages." (PMID 35884829, 2022). "Cordycepin has a profound effect on attenuating the expression of N-cadherin in leukemia and VCAM-1, IL-8 and Il-6 in MSCs." (PMID 28266575, 2017). "Correlating with the increased monocyte viability, the leukemia supernatant (1:3 dilution) induced the secretion of IL-10, TNF-α, IL-6, and IL-1β in both experiments." (PMID 23616009, 2013). "In leukemia microenvironment they play an important and complex role: BMSCs promote AML cell growth and drug resistance via IL-6 secretion, JAK/STAT pathway activation and by activating pro-survival pathways via integrin-linked kinases." (PMID 24304929, 2013). "For example, IL-6 is known to activate STAT3, a key transcription factor in leukemia, leading to the promotion of survival pathways, anti-apoptotic proteins (e.g., BCL-2), and pro-angiogenic factors, all of which contribute to the persistence of leukemia cells in the bone marrow." (PMID 40486651, 2025). "Here, we show that Th17 cells and IL-17A are highly elevated in Ph+ B-ALL patients, which in turn promote the progression of Ph+ B-ALL by activating BCR-ABL, IL6/JAK/STAT3 and NF-kB signalling pathways and increasing the secretion of the chemokine CXCL16 by leukemia cells." (PMID 38172124, 2024). "Further analyses of circulating cytokine levels in these leukemia patient plasma samples via Luminex multiplex assay found a correlation between sSig15 and the cytokines MCP-1/CCL2 and IL6, which have been demonstrated to support the formation of the proleukemic bone marrow microenvironment." (PMID 37465593, 2023). "Reduced IL-6 and TNF-α in LPS activated human leukemia monocytic cell line (THP-1) cells." (PMID 35744969, 2022). "Higher IL-6 values were also found in leukemia survivors; however, there is not much evidence for the role of IL-6 in the pathogenesis of MetS in CCS." (PMID 35743665, 2022). "For instance, Fathi and colleagues recently reported the effect of BM-MSCs upon the reduction of telomerase activity of leukemia cell line, which indicated the therapeutic potential of MSC-derived cytokines (e.g., IL-6, IL-8, TGF-β) for immortality features of hematological tumor cells." (PMID 34174939, 2021). "Co-culture of leukemia cells with bone marrow stromal cells from WT or IL-6 KO mice also did not have an effect on the cells’ sensitivity to doxorubicin." (PMID 34711820, 2021).
leukemia (continued). "Here, we establish that three interventions, IL-6 inhibition, doxorubicin treatment, and PD-L1 blockade, each of which alone fails to promote lasting anti-leukemia immunity, achieve much more durable responses in combination." (PMID 34711820, 2021). "A recent study suggested that increased levels of IL6, TNFA, bFGF, etc. in MSC might be involved in leukemia cells proliferation and chemoprotection." (PMID 29351753, 2018). "Although the biological function of TNIK in hematological cancers, such as MM and leukemia, has not been clearly investigated yet, our results suggest a new approach for treating MM stimulated by exogenous IL-6." (PMID 28467797, 2017). "FIB is induced by IL-6, a cytokine whose expression is enhanced in IPA by our ELISA measurements, perhaps suggesting that an IL-6-FIB pathway is activated in response to angioinvasion in patients with leukemia." (PMID 26581097, 2015). "Furthermore, TBr was also able to suppress the IL-6 induced phosphorylation of STAT3 (Y705 and S727) in human leukemia HL-60 and K-562 cells." (PMID 25383546, 2014). "Furthermore, we proposed to evaluate the patterns of dendritic cell lineages and of a subset of immunomodulatory cytokines (IL-10, TNF-α, IL-6, and IL-1β) during the course of ITD+ leukemia." (PMID 23616009, 2013). "GITRL signaling into various leukemia cells induced the production of TNF-α, IL-6, and IL-8, or IL-10 that not only enhanced proliferation and survival of leukemia cells but also could suppress the immune system." (PMID 23316193, 2012). "High values of some systemic inflammatory cytokines (IL-6, IL-8, and TNF-α) in children with leukemia before the initiation of chemotherapy have been reported, and the authors concluded that elevated concentrations of inflammatory biomarkers could be a risk contributor for oral mucositis." (PMID 41149097, 2025). "Furthermore, pro-inflammatory cytokines such as interleukin (IL)-6 and TNF produced by leukemia cells have a central role in the promotion of disease development by promoting differentiation of leukemic progenitors and by simultaneous disruption and alteration of normal HSC function." (PMID 36405718, 2022). "In addition, we were not able to detect release of the sIL-6R in co-culture of leukemia cells with bone-marrow stromal cells from WT or IL-6 KO mice." (PMID 34711820, 2021). "In that regard, we evaluated if cytokines (IL-10, TNF-α, IL-6, and IL-1β) proposed by several groups as indicators of a broad range of immunopathological conditions affecting cancer could also serve as potential biomarkers to predict ITD+ leukemia relapse." (PMID 23616009, 2013). "Interestingly, exposure of human leukemia monocytic cells to Aedes aegypti salivary gland extract results in the downregulation of innate immune, antiviral, and inflammatory-related genes, including NF-kB, IFN-β, NLRP3, and subsequently IL-1β and IL-6, among others, at 24–36 hours." (PMID 40272158, 2025). "As-A is shown herein to bind to HDC and exhibit a similar effect on leukemia development resulting in inhibition of several anti-inflammatory genes including TNF, IL1A/B, TNFA1P3, and CXCR2, but not IL6." (PMID 39769192, 2024). "In contrast, a corresponding competition assay in vitro with standard cytokines (interleukin-3 [IL-3], IL-6, and stem cell factor [SCF]) demonstrated that disruption of Cxcr4 in c-Kit+ leukemia cells did not affect cell proliferation." (PMID 32460032, 2020). "In conclusion, lacking exogenous TLR signaling, IL-6 augments short-term engraftment of B-CLL, while in the presence of TLR7 agonists, IL-6 operates as a leukemia suppressor by reducing its evolution." (PMID 32102441, 2020). "Similar results were obtained in U937 leukemia cells under M1-skewing conditions, in which a decrease in EDC4 or Dcp1a expression suppressed the IL-6 production without severely altering the mRNA level." (PMID 25970328, 2015).
leukemia (continued). "A mutant lacking the mymA operon induced significantly less IL-1β, IL-6, RANTES, and MCP-1 in human THP-1 monocyte-like leukemia cells, consistent with our findings of diminished immune responses in primary mouse macrophages by the Tn:Rv3087 mutant." (PMID 21170273, 2010). "In the human early leukemia T cell line, HSB.2, misoprostol, an EP4/EP2/EP3 selective agonist, induces IL-6 mRNA and increases IL-6 secretion, effects related to the activities of PKA but not PKC." (PMID 21209948, 2010). "The resultant MLL/AF9 leukemia cells could be expanded in vitro without limit in the presence of SCF, IL3, and IL6." (PMID 27011118, 2016).
pancreatitis (134 papers, 2008 to 2026). Inflammation of the pancreas. "PGC-1α deficiency markedly enhanced NF-κB-mediated upregulation of Il6 in the pancreas in pancreatitis, leading to a severe inflammatory response." (PMID 38790771, 2024). "We have been studying the IL-6 amplifier, which is a fundamental molecular machinery of inflammation in nonimmune cells and here investigated the relationship between PEP and the IL-6 amplifier activation by using pancreatitis-associated genes." (PMID 38806529, 2024). "We investigated the expression of pancreatitis-associated genes with the ability to act as positive regulators of the IL-6 amplifier; these genes include GGT1, PRSS1, CASR, CTRB1, ABO, SPINK1, and CTRC." (PMID 38806529, 2024). "Since PGC-1α acts as selective repressor of NF-κB towards IL-6 in pancreas, PGC-1α deficiency markedly enhanced NF-κB-mediated upregulation of IL-6 in pancreas, leading to a severe pancreatitis." (PMID 34349610, 2021). "For instance, in a pancreatitis model it was shown that IL-6 deficiency leads to a more severe inflammatory response." (PMID 25994622, 2015). "A previous study also demonstrated that IL-6 is intimately linked with pancreatic necrosis and other organ dysfunction in experimental pancreatitis." (PMID 25604657, 2015). "And treatment of rats with mast cell stabilizer cromolyn sodium has been shown to greatly reduce the expressions of ICAM-1 in the lungs in pancreatitis-associated lung injury and decreased IL-6 release." (PMID 26246867, 2015). "And treatment with mast cell stabilizer cromolyn sodium can reduce the expressions of ICAM-1 in the lungs in a rat model of pancreatitis-associated lung injury and downregulate IL-6 level." (PMID 24369442, 2013). "In addition, genes targeting ADAM17 (Adam17ex/ex mice) and treatments (ADAM17 predomain inhibitors [A17pro]) improved experimental pancreatitis, which was associated with a reduction in the IL-6 transsignaling/STAT3 axis." (PMID 36969002, 2023). "Elevated IL6 has been associated with organ failure and severe pancreatitis and may have a role in the activation of an immortalised PSC-like cell line." (PMID 35408908, 2022). "CER-AP is one of the most commonly used animal models of AP but has few clinical parallels, whereas TLCS-AP mimics gallstone aetiology with necrotising pancreatitis in the pancreatic head associated with moderate to severe systemic manifestations, including greatly elevated serum IL-6." (PMID 25878403, 2015). "Furthermore, it could be shown that IL-6 trans-signaling is responsible for pancreatitis associated lung damage in a mouse model of AP." (PMID 40560328, 2025). "Our data confirm this pattern, while the level of interleukin-6 remained at the same level, and the degree of decrease in IL-22 was associated with the severity of the course – the more pronounced the decrease was observed in patients with the more severe course of pancreatitis." (PMID 39694959, 2024). "Furthermore, TNF‐α, IL‐6 and IL‐1β expression has shown a close correlation with the infiltration of activated inflammatory cells into the pancreas and is also associated with the severity of pancreatitis." (PMID 27957800, 2017). "Overall, AUC values for IL-6 in predicting severe pancreatitis or persistent organ failure ranged from 0.69 to 0.99." (PMID 41590239, 2026). "Studies on the metalloprotease ADAM17 in caerulein-induced pancreatitis showed that an inhibition of ADAM17 reduces IL-6 trans-signaling and leukocyte recruitment into damaged pancreatic tissue." (PMID 40560328, 2025). "In severe cases, pancreatitis can lead to the release of cytokines such as Interleukin-1, Interleukin-6, and Tumor Necrosis Factor-α, which activate neutrophils, monocytes, lymphocytes, and platelets, worsening the inflammatory response." (PMID 40429414, 2025). "For example, hypoxic conditions often lead to the upregulation of interleukin-1β (IL-1β) and interleukin-6 (IL-6), contributing to the inflammatory environment characteristic of pancreatitis." (PMID 40787634, 2025).
pancreatitis (continued). "In pancreatitis-induced lung injury, apigenin was associated with decreased TNF-α, IL-6, and MPO expression, indicating attenuation of both cytokine-mediated and oxidative damage." (PMID 40429525, 2025). "Wild type as well as mice lacking the GP130 receptor on CD4+ T cells showed a comparable systemic increase of IL-6 8 h after onset of pancreatitis." (PMID 40560328, 2025). "Our results suggest that IL-6 significantly regulates the balance between inflammation and immunosuppression during pancreatitis and links the local and adaptive immune reactions." (PMID 40560328, 2025). "Results indicated that IL-6, IL-18, and IL-1β were all significantly elevated in pancreatitis samples." (PMID 40787634, 2025). "Cer-pancreatitis resulted in a significant up-regulation of inflammation markers such as TNFα and IL-6." (PMID 38927047, 2024). "Contrary to expectations, IL-6 deficient mice exhibited more severe tissue injury and higher mortality rates in cerulein-induced pancreatitis, suggesting an anti-inflammatory role for endogenous IL-6." (PMID 39694959, 2024). "Cer-pancreatitis induction resulted in a significant elevation of the inflammation markers TNFα and IL-6, accompanied by the reduction in cell viability in a time-dependent manner, indicating that prolonged (24 h) cer treatment mimic AP state in vitro." (PMID 38927047, 2024). "ET-1 is considered a risk factor for pancreatic diseases, especially acute ischemia and pancreatitis, as it induces the secretion of pro-inflammatory cytokines (IL-1, IL-6), which exacerbate existing pancreatitis and lead to disease progression." (PMID 36979645, 2023). "We observed a steady increase in the expression of FOXP3, LRRC32, as well as FOSL2 and IL6 from normal through pancreatitis to PAAD." (PMID 36932385, 2023). "IL-1β, TNF-α, IL-6, IL-8, and IL-18 are widely reported pro-inflammatory cytokines that are key indicators for the early prediction and diagnosis of pancreatitis." (PMID 35663952, 2022). "The inflammatory cytokine IL-6 is a highly suitable prognostic marker for severe pancreatitis, as IL-6 levels correlate with disease severity in both experimental and human pancreatitis." (PMID 35326169, 2022). "Inflammatory cells are activated, exhibit direct cytotoxicity, or release pro-inflammatory cytokines such as IL-1β and IL-6, which are crucial in the beginning of a number of pathological processes in pancreatitis." (PMID 36232419, 2022). "Subsequently, in the in vitro experiments, the AR42J and HPDE6-C7 pancreatitis models induced by caerulein confirmed that overexpression of SNHG11 can reduce the expression of inflammatory factors IL6, IL1-β, and TNF-alfa." (PMID 36611865, 2022). "The administration of gs-4997 to mice with pancreatitis largely reduced the upregulation of IL-6, IL-1β, TNF-α, and MCP-1." (PMID 36316322, 2022). "The fact that pancreatitis is an inflammatory condition is supported by increases in parameters associated with inflammation, such as C-reactive protein (CRP), Interleukin 6 (IL-6) and Tumor necrosis factor α (TNF-α), as well as histologic findings." (PMID 34256804, 2021). "They found that IL‐6 ≥ 28.90 pg/mL had a sensitivity of 62.86%, specificity of 80%, and positive predictive value (PPV) of 95.65%, demonstrating that IL-6 is the best among the tested biomarkers for predicting the progression to severe pancreatitis." (PMID 34349610, 2021). "In a mouse model of pancreatitis, pretreatment with the nicotinic receptor antagonist mecamylamine resulted in more severe pancreatitis increasing edema, plasma hydrolases, and IL-6 levels." (PMID 32265899, 2020). "During pancreatitis, serum amylase, lipase and cytokine, such as IL6, IL-1β and TNF-α, levels are increased." (PMID 32842687, 2020). "It is also accompanied by STAT3 hyperactivation, probably due to the high IL-6 plasma levels achieved in PGC-1α KO mice during pancreatitis." (PMID 32961723, 2020).